ENSG00000293570 (endogenous retrovirus group S71 member 1, envelope)
Gene: Protein-coding gene on chromosome 19 (20,358,163 to 20,371,960, forward strand). Ensembl gene ENSG00000293570.
Gene Ontology:
Biological process: syncytium formation by plasma membrane fusion
Cellular component: plasma membrane
Homologues: Orthologues: rat LOC102549747 (27% identical), mouse BC035947 (23% identical). Paralogues in human: ERVW-1 (16% identical), ERVFRD-1 (13% identical), ERVMER34-1 (11% identical), ERVV-2 (10% identical), ERVV-1 (9% identical), ERV3-1 (9% identical).